CXCL2 (C-X-C motif chemokine ligand 2)
Diseases named in the same sentence as CXCL2 in open-access papers (continued):
Sharing a sentence is not in itself a finding about the gene and the disease.
pneumonia (14 papers, 2014 to 2025). An acute, acute and chronic, or chronic inflammation focally or diffusely affecting the lung parenchyma, caused by an infection in one or both of the lungs (by bacteria, viruses, fungi, or mycoplasma.). "Finally, antibodies against the CXCL2 protein, a neutrophil chemo-attractant, were found to reduce mortality from influenza-associated pneumonia in mice." (PMID 26393920, 2015). "Similar to ex vivo studies detailed above, both IL-6 and CXCL2 mRNA expression was significantly enhanced in anti–LOX-1 mice following 24 hours of pneumonia." (PMID 36264633, 2022). "Pre-existing T. spiralis infection decreased lung neutrophil recruitment, inflammatory mediator IL-1β and IL-6 expression and chemokine CXCL1 and CXCL2 release during P. aeruginosa- pneumonia." (PMID 35500031, 2022). "Pneumonia induced by K. pneumoniae or LPS is associated with the overproduction of IL-1β and neutrophil-related chemokines such as CXCL1, CXCL2, and CXCL6." (PMID 35682923, 2022). "Consistent with increased injury, multiple inflammatory cytokines were significantly upregulated following LOX-1 neutralization in response to pneumonias induced by either E. coli or S. pneumoniae, some of which were the same across both challenges (CXCL2, G-CSF)." (PMID 36264633, 2022). "To obtain an initial understanding of how SRT1720 affects the inflammatory response in the airways during Klebsiella-induced pneumonia, we measured cytokines (IL-6, TNF-α) and chemokines (CXCL1 and CXCL2) in BALF obtained 24 or 42 h after infection." (PMID 41096578, 2025). "Using a murine model of pneumonia, we found that siderophore secretion by K. pneumoniae induces the secretion of interleukin-6 (IL-6), CXCL1, and CXCL2, as well as bacterial dissemination to the spleen, compared to siderophore-negative mutants at an equivalent bacterial number." (PMID 27624128, 2016). "The pleural levels of Groα/CXCL1 and Groβ/CXCL2 in pneumonia patients have not been investigated previously; the role of these two cytokines may need further study." (PMID 33469074, 2021). "In the absence of CXCL5, CXCL1, and CXCL2 bind to the Duffy Antigen Receptor for Chemokines (DARC) to increase the neutrophil infiltration in the lungs, which enhances bacterial clearance, and protects the animal from severe pneumonia." (PMID 32849610, 2020).
myocardial infarction (13 papers, 2013 to 2024). Gross necrosis of the myocardium, as a result of interruption of the blood supply to the area, as in coronary thrombosis. "CXCL2, a chemokine that recruits neutrophils, is elevated after acute myocardial infarction (AMI) and contributes to inflammation-mediated myocardial injury." (PMID 37422588, 2023). "Myocardial infarction is closely associated with hypoxia-related genes such as SELP, CXCL2, MyD88, and S100a8 and genes related to Atf3, PTGS2, Cxcl1, and Socs3 ferroptosis." (PMID 37181809, 2023). "It is reported that high levels of Cxcl2 in the heart tissue aggravated myocardial infarction, and blocking Cxcl2 and its receptors reduced the infarct sizes." (PMID 33664937, 2021). "Using pharmacologic inhibition of circulating Cxcl2, researchers found neutrophil recruitment reduced at the site of myocardial infarction and injury within the infarcted myocardium alleviated." (PMID 31772617, 2019). "In the heart, CXCL2 expression rises in response to myocardial infarction, and studies have shown that pre-conditioning of MSCs with CXCL2 increases post-transplant stem cell survival rates." (PMID 23755141, 2013). "Based on the inflammatory and fibrotic markers commonly observed in response to myocardial infarction and development of heart failure, we assessed the expression of mRNA for Tnfa, Il1b,Il6, Il18, Ccl2, Ccl3, Cxcl1, Cxcl2, Col1a1, Col3a1, Postn, and Tlr4 at 1 and 3 months." (PMID 35411847, 2022). "During the acute phase of myocardial infarction (MI) in the adult heart, resident macrophages recruit leucocytes (by secreting CXCL2 and CXCL5) and monocytes (by secreting CCL2) to the ischemic area." (PMID 33130914, 2021). "Thus, Cxcl2 may play a key role in regulating cardiac remodeling following myocardial infarction (MI)." (PMID 31772617, 2019). "CXCL2 is believed to be a critical therapeutic target in myocardial infarctions (MI)." (PMID 33986658, 2020).
cervical cancer (12 papers, 2021 to 2023). A primary or metastatic malignant neoplasm involving the cervix. "CXCL2 is associated with lymph node metastasis in cervical cancer." (PMID 36591476, 2022). "CXCL2 expression level was closely related to lymph node metastasis and prognosis of cervical cancer patients." (PMID 37007965, 2023). "In cervical cancer, upregulation of CXCL1/CXCL2 is associated with malignant tumor phenotypes (larger tumor size, lymph node (LYN) metastasis, and shorter patient survival)." (PMID 36612163, 2022). "Then, we constructed a risk score model based on LPIN2, TEKT2, CXCL2, and FABP4, which had high accuracy in predicting the prognosis of cervical cancer patients." (PMID 34789197, 2021). "Furthermore, only four genes (CXCL2, SDC1, has-miR-221-3p, and has-miR-222-3p) were associated with OS in cervical cancer." (PMID 36591476, 2022). "In cervical cancer, CXCL2 may promote tumor growth and angiogenesis and NF-κB pathway is involved." (PMID 34789197, 2021). "Therefore, we supposed that CXCL2 may lead to activation of neutrophils signaling and result in poor prognosis in cervical cancer, which deserves further research." (PMID 34789197, 2021). "Epiregulin was positively correlated with most chemokines, such as CXCL1, CXCL2, CXCL3, CXCL5, CXCL6, CXCL8, and CCL20, in most types of cancer, including cervical cancer." (PMID 37020674, 2023). "This study revealed that the presence of HPV16 and 18 oncogenes significantly alter the expression of CCL28, CXCL1, CXCL2, CXCL3, CXCL6, CXCL8, CXCL10, and CXCL11; overexpression of those chemokines was also confirmed in cervical cancer biopsies." (PMID 37893029, 2023). "Our results revealed that expression of CXCL1, CXCL2, CXCL3, and CXCL8 increases in the presence of E6/E7 of HPV16 and 18, are overexpressed in CC biopsies, and that their higher expression is related to a worse prognostic survival in cervical cancer." (PMID 37893029, 2023). "It is reported that CXCL1, CXCL2, and CXCL8 are related to the tumor growth in cervical cancer." (PMID 36284631, 2022). "Therefore, AKIP1 is critical to the angiogenesis and growth of cervical cancer by increasing levels of the NF-κB-dependent chemokines CXCL1, CXCL2, and CXCL8." (PMID 34833360, 2021). "AKIP1 in cervical cancer cells stimulates the expression of CXCL1, CXCL2, and CXCL8." (PMID 34833360, 2021).
prostate carcinoma (12 papers, 2007 to 2025). A carcinoma that arises from epithelial cells of the prostate gland. "In this study, we profiled the cytokine-chemokine serum levels associated with prostate cancer and demonstrated that serum chemokines CXCL2, CXCL5, and CCL23 are the most distinguished chemokines differentially expressed in men of AA and CA races." (PMID 37698493, 2023). "Cycling hypoxia increases the expression of both described chemokines (CXCL1 and CXCL2) in PC-3 prostate cancer cells and SK-OV-3 ovarian adenocarcinoma cells." (PMID 33467722, 2021). "As CXCL1 and CXCL2 were predicted as downstream targets of NFκB in prostate cancer, we suggest SELE as another important downstream target in this process." (PMID 27078000, 2016). "Our prediction of the chemokine (C-X-C motif) ligand 1 and 2 (CXCL1, CXCL2) as direct and indirect downstream targets of NFκB in prostate cancer can be supported by previous finding in different contexts." (PMID 27078000, 2016). "Notable genes in the predicted pathway included ATF3, JUNB, KLF6, NR4A2, ZFP36, DUSP5 and NEDD9, as well as STAT3 and IRF1 as novel upstream regulators, and SELE, CXCL1 and CXCL2 as novel downstream targets of NFκB in prostate cancer." (PMID 27078000, 2016). "Furthermore, castration-induced CXCL1, CXCL2 and IL-8 from prostate cancer cells mediate myeloid infiltration, particularly of MDSCs, resulting in an immunosuppressive TME17,18." (PMID 39633050, 2025). "Lower levels of CCL23 in AA prostate cancer patient sera and tumor tissues and high CXCL2 and CXCL5 may contribute to aggressive prostate cancer, as often seen in AA men." (PMID 37698493, 2023). "Serum levels of CXCL2 and CXCL5 exhibited race-specific differences, while CCL23 showed both race- and cancer-specific differences supporting the potential contribution of systemic chemokines in differential outcomes among races in association with prostate cancer." (PMID 37698493, 2023). "Mechanistically, we found that SERPINA3 may influence the expression of CXCL2 to activate the IL-17 and TNFα signaling pathways, thereby mediating the recruitment of M1 macrophages in the tumor microenvironment and exerting an inhibitory effect on prostate cancer progression." (PMID 40367014, 2025). "In prostate cancer (PCa), BMAT releases chemokines CXCL1 and CXCL2, which induce osteoclastogenesis through CXCR2 signaling." (PMID 38625510, 2024). "Due to increased circulatory CXCL2 and CXCL5 levels, AA men likely acquire a disadvantage with vulnerable immune surveillance, leading to aggressive prostate cancer, as often seen in AA men at diagnosis." (PMID 37698493, 2023). "Selected chemokines (CXCL2, CXCL5, and CCL23) serum level was validated in 211 serum samples from prostate cancer patients and healthy controls." (PMID 37698493, 2023). "In humans, both CXCL2 and CCL5 have been suggested to promote prostate cancer development and indeed increased CCL5 levels were observed in human prostate cancer." (PMID 29212195, 2017). "Our predicted NFκB pathway suggested 8 novel genes which were found to be highly down-regulated in lethal prostate cancer and highly functionally related to NFκB, namely ATF3, CXCL2, DUSP5, JUNB, NEDD9, SELE, TRIB1, and ZFP36." (PMID 27078000, 2016). "In contrast, race-specific differences were observed for significantly higher serum levels of CXCL2 (p < 0.0001), CXCL5 (p = 0.016), and IL-6 (p = 0.004), and lower levels of CCL23 (p < 0.0001) and CCL27 (p = 0.016) in AA prostate cancer patients (n = 14) compared to CA (n = 14)." (PMID 37698493, 2023). "In summary, the elevated serum chemokines CXCL2 and CXCL5, in conjunction with a low level of CCL23, may contribute towards suppressed antitumor immunity and account for lethal prostate cancer in AA men." (PMID 37698493, 2023).
gastric cancer (10 papers, 2014 to 2024). A primary or metastatic malignant neoplasm involving the stomach. "Interestingly, expression of the chemokine (C-X-C motif) receptor 2 (CXCR2) ligands CXCL2 and CXCL3 has been recently shown to contribute to the malignant progression of gastric cancer." (PMID 37193047, 2022).
injury (10 papers, 2012 to 2026). Damage inflicted on the body as the direct or indirect result of an external force, with or without disruption of structural continuity. "CXCL2 is an antimicrobial cell-signaling cytokine and a chemoattractant with a pro-inflammatory function and linked to ventilator and hyperoxia-induced acute lung injury, and it contributes to chemotaxis, and immune and inflammatory response after infection." (PMID 32670284, 2020). "In addition, IL-1β, IL-6, TNFα, and the chemokines CCL5 and CXCL2 (which were all upregulated by LPA in primary microglia) are implicated as modulators of the neuroinflammatory response during traumatic brain injury where LPA levels are increased." (PMID 27565558, 2016). "Hepatocyte death is reduced by 5 ng/mL each of CXCL1 and CXCL2, and CXCL2 promotes liver regeneration and protects against adenovirus- and acetaminophen-induced liver injury." (PMID 39619227, 2023). "Thoracic trauma increased neutrophil chemokine production as shown in BAL with Cytokine-induced neutrophil chemoattractant 3 (CINC-3, MIP-2, GRO beta, or CXCL2), a member of the CXC subfamily of chemokines, peaking in the alveolar space about at 6 h." (PMID 36928833, 2023). "BAL levels of CXCL1, CXCL2, IL-1β, TNFα and TGFβ were increased during the early phase, while IGF-1 levels were significantly increased in the later phase, suggesting that IGF-1 is involved in the resolution processes of acute lung injury." (PMID 41431237, 2026). "Genes that encode inflammatory cytokines (such as TNF and IL1), chemokines (such as CCL2, CXCL1, CXCL2, and CXCL3) and cell proliferation-related proteins (such as CycD and CycE) were downregulated when Cyp2c29 was overexpressed in a mouse model of liver injury." (PMID 32587777, 2020).
lung adenocarcinoma (9 papers, 2018 to 2025). A carcinoma that arises from the lung and is characterized by the presence of malignant glandular epithelial cells. "It has recently been demonstrated that CAV1 as well as PPARG are associated with a favorable outcome in lung adenocarcinoma, while the cytokine CXCL2 might be a predictor for immunotherapy response." (PMID 34831349, 2021). "In liver hepatocellular carcinoma and lung adenocarcinoma, CXCL2 and PPBP negatively correlated with proliferation, and were the only CXCR2 ligands that negatively correlated with the count of MDSCs." (PMID 37686093, 2023). "CXCL2 produced by CAFs increases the potential to induce PD-L1 expression in lung adenocarcinoma cells." (PMID 36275750, 2022). "In this study, we particularly focused on CXCL2, a chemokine released from CAFs in lung adenocarcinoma cells." (PMID 31462002, 2019). "CXCL2 is therefore considered to have a potential to induce PD-L1 expression in lung adenocarcinoma cells as a result of an interaction between carcinoma cells and CAFs." (PMID 31462002, 2019). "CAFs increased PD-L1 expression in lung adenocarcinoma cells through the secretion of soluble factors, including CXCL2." (PMID 31462002, 2019). "Conditioned medium of primary cultured CAFs increased PD-L1 mRNA level in lung adenocarcinoma cell lines more than CXCL2 did." (PMID 31462002, 2019). "Furthermore, CAF have been shown to increase PD-L1 expression on different lung adenocarcinoma cell lines via CXCL2 secretion and signaling." (PMID 37207152, 2023). "However, CAFs increased PD-L1 expression in lung adenocarcinoma cells through the secretion of soluble factors, such as CXCL2." (PMID 31462002, 2019). "Similarly, Stk24 silencing inhibited the IL-17-induced expression of IL-6, CXCL2, and CCL20 in human lung adenocarcinoma cells A549." (PMID 29760709, 2018). "Considering the environment of KRAS-promoted lung adenocarcinoma, CUL4B exerts its tumor-suppressing capabilities via intricate epigenetic processes that encompass coordinated interplay with HDACs, ultimately inhibiting the transcription of C-X-C motif chemokine ligand 2 (CXCL2)." (PMID 40230836, 2025).
mastitis (9 papers, 2018 to 2026). Inflammation of breast tissue during lactation or postpartum due to an obstructed duct or infection. "Collectively, these findings establish CXCL2 as a putative molecular marker for mastitis resistance breeding and provide a foundational resource for deciphering the molecular mechanisms governing mammary health." (PMID 42274481, 2026). "As previously reported in other tissues, CXCL1 (KC), CXCL2 (MIP2), ICAM-1, ACKR1, Selp (P-selectin), and Itgam (Cd11b), are all most probably involved in transendothelial neutrophil trafficking in mastitis." (PMID 37032878, 2023). "In dairy cow studies, the expression of CXCL2 and CXCL3 increased when treated with LPS or lipoteichoic acid (LTA), which are derived from major mastitis pathogens such as E. coli and Staphylococcus aureus in bovine, mammary, epithelial cells." (PMID 33374309, 2020). "Some of the highly connected genes in the purple module have previously been related to mastitis development including NFKBIZ, NFKBIA, CXCL2, GRO1, CXCL3, LPIN1, and DAB2." (PMID 32754201, 2020). "For example, CXCL2 and CXCL8 have been identified as the most informative genes and as candidate biomarkers of bovine mastitis, suggesting their possible effects on cow’s ability to resist mastitis." (PMID 36336691, 2022). "The weakened neutrophil functions concomitant with reduced CXCL2 and CXCL3 expression at high environmental temperatures may explain the increased infectious diseases such as mastitis in heat-stressed, dairy cows." (PMID 33374309, 2020).
cholestasis (8 papers, 2019 to 2025). Impairment of the bile flow caused by obstruction within the liver, or outside the liver in the bile duct system. "As cholestasis progresses, excessive primary bile acids that accumulate in the liver intoxicates hepatocytes, which lead to exacerbated release of chemokines, particularly CXCL2 and CXCL5." (PMID 38951890, 2024). "Various molecules such as CCL2, CXCL1, CXCL2, and ICAM-1 have been reported to be important in neutrophil trafficking in the liver, which explains why liver injury occurs during cholestasis." (PMID 32701506, 2020). "Therefore, we isolated the hepatocytes from normal mice and treated them with GCA or TCA in vitro clarify the producing of CXCL2 and CXCL5 in cholestasis liver." (PMID 38951890, 2024). "The most plausible is that cholestasis induces the release of BA-induced pro-inflammatory cytokines (TNF-α, chemokine CCL2, chemokine C-X-C motif ligand 2, and CXCL2, among others) by hepatocytes in addition to the responses of cholangiocytes and the innate immune cells in liver." (PMID 31546715, 2019).
co-infection (8 papers, 2011 to 2023). "Furthermore, co-infection triggered the upregulation of Ccl2, Cxcl2 and Tnf, which were significantly less pronounced in comparison to GAS infection only." (PMID 36365071, 2022). "In addition, CCL4, CXCL1, and CXCL2 expression in the co-infection group was highly significant, while CX3CL1 and XCL1 expression was equivalent to that in mock control." (PMID 33968006, 2021). "Additionally, pro-inflammatory cytokines IL-1β, IL-6, CXCL2, and TNF-α are downregulated during co-infection compared to P. aeruginosa single-infection." (PMID 37305417, 2023). "In addition, type I IFN production during IAV/bacterial coinfection has been shown to suppress CCL2, CXCL1, and CXCL2 levels and subsequently inhibit the recruitment of monocytes and neutrophils." (PMID 30420852, 2018). "Surprisingly, only two chemokines involving neutrophil recruitment were modulated after L. major (co-)infection: a clear increase was detected for CCL3 and CXCL2, although statistically not significant." (PMID 34310619, 2021).
diabetes (8 papers, 2020 to 2025). "Prior studies have associated CXCL1 and CXCL2 with neutrophil infiltration and myocardial injury in diabetes; our results expand on this by connecting CXCL1 expression to EndMT regulation, a link that remains relatively underexplored." (PMID 40426976, 2025). "Neutrophils expressing CXCR1/2 can be recruited to the pancreas by murine β cells, and macrophages produce C-X-C motif ligand 2 (CXCL2) in autoimmune diabetes, which plays a vital role in the early stages of diabetes." (PMID 32377527, 2020). "Intriguingly, the hematopoietic depletion of NOD1 mitigated the diabetes-induced expression of CXCL1 and CXCL2; TNFα and IL10 remained unaffected." (PMID 38336763, 2024). "There is also a link to diabetes as insulin signaling lowers LPS-induced CXCL1 expression in gingival fibroblasts, and short-chain fatty acid can lower cytokine-induced expression of CXCL1 and CXCL2 in HSC2 cells and gingival fibroblasts." (PMID 37762294, 2023).